CD4 (CD4 molecule)
Diseases named in the same sentence as CD4 in open-access papers (continued):
Sharing a sentence is not in itself a finding about the gene and the disease.
tumor (continued). "Furthermore, three tumor-infiltrating immune cell subsets, including naïve B memory cells, memory B cells, and CD4 memory resting T cells were present in significantly higher fractions in high-risk patients as compared with low-risk patients (p < 0.05)." (PMID 33194633, 2020). "In addition, we found that CD4+TIM-3+ TILs potentially support tumor invasion and metastasis, compared with conventional CD4+CD25+ Tregs in the CRC TME." (PMID 32041340, 2020). "Moreover, LAG3 expression in conjunction with PD-L1 expression has been demonstrated on tumor infiltrating CD4+ and CD8+ T cells and during the course of tumor cell - immune cell interaction." (PMID 32861198, 2020). "Similarly, the tumor suppression induced by Agpat4 silencing in immunocompetent mice was fully prevented by anti-CD8 or anti-CD4 neutralizing antibodies." (PMID 32296017, 2020). "In NSCLC tumor and blood samples, scRNA-seq allowed to identify seven CD4+ T cell populations." (PMID 32265933, 2020). "Though generation of early memory CD4+ T cells could be beneficial for a long-term anti-tumor effect, they can influence CD8+ T cell expansion and function depending on their helper subset." (PMID 32504246, 2020). "Whether Th17 cells will convert into other CD4 T cells at the tumor site or whether they will convert at the periphery and will then be recruited within the tumor is unknown." (PMID 32121394, 2020). "This increased control may be attributed to an overall increase in the CD45+ fraction of tumor cells including CD4+ and CD8+ T cells, as well as CD11c+ cells." (PMID 33339195, 2020). "In this study, we described the immune landscape of the OSA tumor microenvironment, along with its heterogeneity, and uncovered the abundant and predominant infiltration of relevant immune cell subtypes (CD4+ Th1 cells and CD68+ macrophages) in the microenvironment." (PMID 32850346, 2020). "Considering different proportions in tumor and normal tissues, CD4-GZMA cells may play an important role in HCC patients' prognosis." (PMID 33043022, 2020). "However, the role of CD4+ memory T cell in tumour microenvironment is still poorly understood, and more studies are needed." (PMID 32047563, 2020). "Increased CD4+FOXP3+ T‐cell density in the GC tumor correlated with prolonged survival." (PMID 32377339, 2020). "The CIBERSORT results showed that mainly CD8+ cells, activated CD4 memory cells and M1 macrophages are the ones highly infiltrated in a tumor in a condition of high immune infiltration, and these cells are important anti-tumor immune cells." (PMID 33628734, 2020). "Bregs may suppress the T cell-mediated anticancer immune response in the tumor microenvironment by inducing the CD4+ T cell conversion into Tregs, promoting tumor progression and metastasis." (PMID 33230233, 2020). "Interestingly, a study revealed a tumor-induced subset of “regulatory B cells” able to favor differentiation of resting CD4+ T cells into Tregs." (PMID 33207601, 2020). "Nevertheless, our findings are significant because they support and help to explain efficacy of YAP inhibitors in the treatment of cancer, as YAP appears to not only play a pro-oncogenic role in tumor cells but also promotes suppression of both CD4 and CD8 T cells." (PMID 32322254, 2020). "PD-1 and CTLA-4, the two most commonly studied checkpoints, are not functionally redundant and while they both act to modulate distinct populations of tumour-infiltrating lymphocytes (TILs), including CD4+, CD8+, regulatory T (Treg) cells, they do so with different mechanistic profiles." (PMID 32705455, 2020). "To verify whether immunological CD4+ T cell changes were really related to the tumor burden, we monitored Th1, Th2, Th17, and Treg cell levels before and after the operation in UCC or CIN patients." (PMID 32552719, 2020).
tumor (continued). "Consistent with previous results, depletion of CD4+ T cells paradoxically enhanced the therapeutic effect of combination therapy in local tumor control, whereas depletion of CD8+ T cells abolished the therapeutic effects of the combination therapy in abscopal tumors." (PMID 33171765, 2020). "The results show that RNF183 expression has negatively correlations with tumor purity (r = −0.063, p = 2.85E–01), infiltrating levels of CD4 + T cells (r = −0.064, p = 2.74E–01), neutrophils (r = −0.126, p = 3.17E–02), and dendritic cells (r = −0.042, p = 4.78E–01)." (PMID 33324448, 2020). "In fact, the impairment in tumor growth after CD4+ T cell depletion could be mediated by the elimination of the CD4+ Treg cells." (PMID 33126649, 2020). "Activation of T cells in TIME inhibits tumor cells, and this may explain why CD8+ T cells and CD4+ T cells in TIME T2/T3 were associated with good prognosis." (PMID 33072579, 2020). "Another study demonstrated that intra-tumor injection of rat UC-MSCs significantly attenuated tumor growth and concomitantly increased intra-tumor infiltration of CD4+ and CD8+ T cells and NK cells and decreased levels of intra-tumor macrophages and Treg cells." (PMID 32637408, 2020). "The combination of either CD4 or CD68 with CSF1R predicted a more favorable prognosis (p < 0.01), suggesting that coordinated interaction between tumor antigen-specific CD4+ Th1 cells and CSF1R might participate in macrophage polarization toward CD68+ M1 TAM." (PMID 32850346, 2020). "The correlation of SCARF1 with CD4+ T cell tumor infiltration and its role in recruitment may help in the identification of patients who will respond to immunotherapies." (PMID 34354939, 2020). "Tumor tissue analysis showed an important infiltration of T-helper lymphocytes (TH, CD4+)." (PMID 32423101, 2020). "Analysis of cells in the 9464D-GD2 tumor microenvironment on treatment day 13 revealed an increase of CD4+ T cells, monocytes (Mono)/macrophages (Mac), CD8 to Treg ratio, and reduction of Tregs, whereas the percentages of NK cells and neutrophils were unchanged." (PMID 31810498, 2019). "Our results show a decreased ratio of CD4+/CD8+ lymphocytes in tumours and TDLN of H4R-KO mice that could contribute for the slower growth rate of these tumours." (PMID 29988113, 2019). "To definitively determine whether the tumor-protective effects of DC depletion were CD4+ T-cell dependent, we ablated DC in PDA-bearing hosts in the context of CD4+ T-cell depletion." (PMID 30926808, 2019). "CCR5 potentiates CD4 T helper cell functions boosting overall anti-tumor responses." (PMID 31307539, 2019). "The complex ofimmune reactions is mediated by T cells, which not only trigger and stimulate(CD4+ T cells, T-helper cells (Th)) or regulate (regulatory T cells(Treg)) the immune response, but also destroy infected or tumor cells(CD8+ killer T cells, cytotoxic T cells)." (PMID 31993233, 2019). "There is accumulative evidence demonstrating that FoxP3+CD25+CD4+Treg cells prevent immune responses to cancerous cells and further demonstrating the Treg cells role in promoting tumour growth through inhibiting vaccine-stimulated antitumor immune reactions and preventing successful tumor control." (PMID 30693029, 2019). "Moreover, cryo-thermal-induced macrophage polarization to the M1 phenotype was required for phenotypically matured splenic DCs to promote tumor-bearing CD4+ T-cell differentiation into Th1 and CD4-CTL." (PMID 30833570, 2019). "Importantly, this compartment was highly protective as mice subsequently challenged with B16 tumors were protected unless CD4+ (or CD8+) T cells were depleted prior to tumor challenge." (PMID 31379821, 2019). "Tumor-secreted cytokines convert naïve CD4+ T cells to Tregs in the tumor microenvironment." (PMID 30979375, 2019).
tumor (continued). "Antigen-specific CD4 T cells can improve expansion of cognate and tumor-specific memory CD8 T cells, enhance recruitment and infiltration of CD8 T cells into tumors, help overcoming immunosuppressive reactions in the tumor microenvironment, and facilitate adoptive CD8 T cell tumor therapy." (PMID 31333674, 2019). "We next assessed whether the recognition of PD-L1241-265-specific CD4+ T-cells is surely dependent on PD-L1 expression in tumor cells." (PMID 31221178, 2019). "Moreover, evidence for the involvement of CD4+ T cells in tumor eradication extends beyond the canonical function of helper T cells and their ability to promote CD8+ T cell and B cell responses." (PMID 31379821, 2019). "However, several characteristics of CD4+ T cells place them as required players for efficacious anti-tumor immunity." (PMID 31754392, 2019). "Tregs are functionally immunosuppressive and could directly or indirectly inhibit the proliferation of other CD4+ T cells via cytokines to further decrease local immunologic responses to tumor cells." (PMID 30824840, 2019). "The inhibitory effect of SM16 on primary tumor growth was associated with a significant increase in CD4+CD25–FoxP3+ in the spleen but not in the tumor draining lymph nodes or tumor." (PMID 31288845, 2019). "This could make way for further studies exploring different approaches of immunotherapy such as vaccination in combination with ACT using tumor specific CD4+ T cells." (PMID 30956760, 2019). "Splenic CD4+ T cells were isolated from tumour-bearing mice on day 15 following tumour inoculation, and co-cultured with eosinophils from tumour-bearing mice on day 15 following tumour inoculation or cryo-thermal treated mice on day 3 at a ratio of 5:1 for 24 h." (PMID 31519961, 2019). "Therefore, we next measured the production of the effector cytokines IFNγ and TNFα by tumor-associated CD8+ and CD4+ T cells in our involution group tumors." (PMID 31244852, 2019). "Notably, tumor growth inhibition seen following administration of B. rodentium was also accompanied by enhanced tumor infiltration of CD4+ and CD8+ T cells and cytokine production, confirming activation of antitumor immunity by specific gut microbiota." (PMID 30940817, 2019). "In addition, high CD8+ tumor-infiltrating T cells were shown to be a favorable prognostic factor for right-sided colon tumors and increased levels of CD4+ and CD8+ T cells in colorectal TME were shown to correlate with improved response to chemo-radiotherapy." (PMID 31921188, 2019). "It is also possible that other immune cell populations such as increases in regulatory T cells, myeloid-derived suppressor cells or tumor-associated macrophages or lack of CD4+ T-cell help contribute to the observed TAA-specific CD8+ T-cell alterations." (PMID 31497249, 2019). "However, high concentration of IL-24 notably down-regulated FoxP3 mRNA relative level in both peripheral and tumor-infiltrating CD4+ T cells (Tukey tests, P < 0.0001)." (PMID 31921658, 2019). "It has been shown that BCG-stimulated PBMCs induce death of tumor cell lines through a complex mechanism involving the activation of macrophages and CD4+ T cells, which leads to the generation of BCG-activated killer cells (BAK cells - CD8+ T cells) stimulated by IL-2 and IFN-γ." (PMID 31297119, 2019). "Especially, immunotherapies aiming at activating CD8+ and CD4+ T cells or reversing their immunosuppression may be effective to restrain tumor metastasis." (PMID 31297335, 2019). "These remarks support our previous observation in co-culture set-up and suggest that KMO and KYNU may play a role in district CD4+ T-cell behaviour in tumour immunity." (PMID 31434983, 2019). "On the other hand, CD4+ T lymphocytes play complex and important roles in tumor immunity." (PMID 31612115, 2019).
tumor (continued). "In the present study, we performed a comprehensive comparison between HHLA2 and PD-L1 in terms of the expression pattern, clinical relevance and their associations with tumor infiltrating CD3+, CD8+, CD4 + Foxp3+, CD68+, CD163+ and CD20+ immune cells in a ICC cohort after curative resection." (PMID 30885276, 2019). "However, a study revealed that the CCA patients with tumor-infiltrating CD4+ T cells, CD8+ T cells, and Treg cells showed a significantly longer overall survival." (PMID 31620360, 2019). "Since fractionated RT can induce PD-1 expression in tumor infiltrating CD4+ and CD8+ T cells hours after treatment, checkpoint blockade administered at this time likely blocks the PD-1/L1 signaling axis thereby augmenting T cell responses and preventing T cell anergy." (PMID 30895168, 2019). "Since cancer vaccination aims at triggering cytotoxic and tumor-specific CTLs, it is important to understand how CD4 T-helper cells may contribute to CTL priming, function and survival in the context of cancer vaccines." (PMID 31333674, 2019). "In addition, antigen-specific CD4+ T helper cells are believed to be critically involved in the induction of optimal anti-tumor responses." (PMID 31130945, 2019). "However, in subsequent analyses we found slightly decreasing T-cell numbers during tumor development in all animals, especially of the CD4+ compartment." (PMID 30972297, 2019). "Therefore, our study is the first to define a bona fide tumor antigen recognized by CD4+CD8+ double-positive T cells in cancer patients." (PMID 30626427, 2019). "It is possible that more infused auto-CAR T cells in such an inhibitory microenvironment of higher tumor burden differentiated into CD4+ Tregs, but expansion of CD8+ cytotoxic T cells was suppressed, unlike infused haplo-CAR T cells where the CD8+ T cell was a main proliferated subpopulation." (PMID 30791947, 2019). "Likewise, persistent STAT5 activity induces (i) transformation, (ii) proliferation, and (iii) anti-apoptotic signals that contribute to hematological malignancies, while also suppressing anti-tumor immunity by expanding CD4+/CD25+ regulatory T cells (Tregs)." (PMID 31684144, 2019). "cDC2 and MoDCs may also cross-present tumor antigens and cDC2 are known to be essential for priming of anti-tumor CD4+ T cell response." (PMID 31736936, 2019). "It showed that activated CD4+CD8+ double positive T cells in tumor and spleen induced by CAH (+) were mostly memory T cells with mostly being central memory cells (CD44high CD62Lhigh phenotypes) and less being effector memory cells (CD44high CD62Llow phenotypes)." (PMID 30886812, 2019). "Also, previous studies on shark cartilage have shown immunological enhancement of CD4/CD8 in murine tumor cells." (PMID 30834079, 2019). "Furthermore, B cell or CD4+ T cell depletion impeded tumor growth by increasing effector T cell function." (PMID 31300052, 2019). "Also, in the MCA205 tumor model, the CD4+ TAI cells were identified and were increased by PD-L1 treatment." (PMID 31412943, 2019). "Tumor-infiltrating lymphocytes (TILs) including CD3+ T cells, CD8+ T cells, Th1 CD4+ T cell could inhibit tumor cell proliferation and metastases." (PMID 31572062, 2019). "Interestingly, a recent study using mass cytometry for analysis of CD4+ T cell subsets in FL patient biopsies, has demonstrated that the frequency of intra-tumor naive T cells correlates with an improved patient survival." (PMID 31530876, 2019). "In this study, cryo-thermal therapy-mediated polarization of macrophages into the M1 phenotype could directly promote anti-tumor CD4+ and cytotoxic CD8+ T-cell activation." (PMID 30833570, 2019). "On the contrary, P2X7 pharmacological blockade in the P2X7 WT host supports a tumor-aggressive infiltrate characterized by a high number of CD4+ effector T lymphocytes (Teff), reduced expression of OX40 on Tregs and of CD39 and CD73 on Teff, and conventional dendritic cells (cDCs)." (PMID 30655604, 2019).
tumor (continued). "Under this proposed model, cross-reactive T cells primed against bacterial antigens might exert anti-tumor effects either by providing help (CD4+ T cells) or through direct killing (CD8+ T cells)." (PMID 30995949, 2019). "Mechanistically, cross-presentation of α-GalCer-loaded tumor cells by DC could prime CD4+ and CD8+ T cell response and provide long-lived immunity." (PMID 31387637, 2019). "Increasing the recruitment of CCR9+CXCR3+CD4+ T lymphocvtes into tumor beds." (PMID 32010123, 2019). "CD3+ TILs in the central tumor area (p = 0.010), CD4+ TILs in the central tumor area (p = 0.045), CD8+ TILs in the central tumor area (p = 0.033), and CD8+ TILs in the invasive margin area (p = 0.004) also showed significant difference between lVI(-) and LVI(+) patients." (PMID 31616592, 2019). "These authors further showed that the survivin peptide cocktail vaccine has high therapeutic efficacy against four different murine tumor models established, and is associated with vaccine capacity to generate both specific cytotoxic CD8+ and multifunctional Th1 CD4+ T-cell responses." (PMID 31439015, 2019). "The positive influence of IgG1 TIBs in KRASmut tumors could be explained by presentation of BCR-cognate tumor antigens to CD4+ T-cells." (PMID 31665076, 2019). "The long-term protective effect of CD4+ TEM against tumor has been confirmed." (PMID 30999966, 2019). "Interestingly, requirement of CD4 T cell help for optimal CD8 T cell effector functions in the context of tumor immunity is also well-documented, including the ability of CTLs to infiltrate the tumors." (PMID 31143179, 2019). "Importantly, this study suggests that the extracellular potassium released from tumor necrosis inhibits both CD4 and CD8 T cell activities that are critical for anti-tumor immunity." (PMID 31922095, 2019). "Tumor xenografts in nude mice were used for confirming effects of CD4+ T cells in vivo study." (PMID 31018021, 2019). "Similar data were obtained in the setting of adoptive transfer of CD73+/− OT-II or CD73−/− OT-II CD4+CD25- naïve T cells (CD90.2+) into B16-OVA-bearing mice (CD90.1+) for examining the tumor antigen-specific Treg conversion, consistent with the previous results." (PMID 30635578, 2019). "This indicates that CD4 CTLs might contribute tumor immunity against established tumors and may have an important role in immunosurveillance, helping to identify and remove incipient tumor cells abnormally activating class II MHC molecules." (PMID 31719197, 2019). "Importantly, under HPK1 KD conditions, the dLN appear to be better orchestrated to generate a more robust anti-tumor immune reservoir as demonstrated by the augmented levels of CD4+Ki67+ and CD8+Ki67+ T cells." (PMID 30913212, 2019). "Additionally, we observed a 61.3% reduction in Treg percentage among CD4+ T cells in BNL-derived tumor tissue from Fgl2−/− mice." (PMID 31409352, 2019). "Furthermore, our results showed that IBC patients are characterized by a high frequency of the Treg (Foxp3+CD4+) subset representing 23% of total CD4+ T cells drained from the tumor microenvironment." (PMID 31145753, 2019). "Interestingly, the immunostaining results showed a dominant composition of CD4+ TILs in the lymphocytic infiltrate in tumour sections from patient PanTT39 (including the TLS)." (PMID 30377343, 2019). "As shown by a challenging case of rapid CRS onset in HOS-FRα tumor-bearing mice due to a very high dose of 35 million total CAR-T cells (93:7 CD4/CD8), intravenous sodium fluorescein at a human equivalent dose (~95 mg/kg in mice) acted very quickly to reduce CAR-T cell derived human cytokines." (PMID 30941303, 2019). "Lastly, intra-tumor infiltration of Tregs (CD3 + CD4 + FOXP3) was also disrupted by SR9243." (PMID 31863071, 2019). "CD8+ and CD4+ T cells play distinct roles in anti-tumor immune responses." (PMID 30626427, 2019).